IL1B (interleukin 1 beta)
Diseases named in the same sentence as IL1B in open-access papers (continued):
Sharing a sentence is not in itself a finding about the gene and the disease.
infection (continued). "In accordance with the relevant pathological changes, the selected proinflammatory cytokines, including IL-1β, IL-6, and TNF-α, in the infected mice were obviously elevated at 1–3 days post-infection and then maintained a slight upregulation at lower levels at 5 and 7 days post-infection." (PMID 38338106, 2024). "Furthermore, the expression of IL-1β and TNF-α was subsided with lower intensity after 48 h post-infection." (PMID 38965554, 2024). "Whereas some DEGs were up-regulated to comparable levels in all infections (e.g., TNFAIP6), some DEGs, such as IDO1 and IL-1β, were up-regulated to comparable levels in all infections with the virulent reference strains but expressed less in cells infected with the avirulent strain H37Ra." (PMID 39597535, 2024). "Supporting this, whilst both Il1a and Il1b gene expression were increased in LPS-RSV mice on day 1 post infection, only IL-1α and not IL-1β protein was detectable in the airways." (PMID 39127259, 2024). "We excluded genes that are differently expressed in IL-1β-/- mice 6 d.p.i. versus 2 d.p.i. as these mice do not die from the infection, thus these genes are not related with mortality." (PMID 38236896, 2024). "IL-10–mediated inhibition of shedding GC-associated cervical epithelial cells in the presence of the potent inflammatory cytokines IL-1β and TNF-α underscores the importance of the direct interaction of IL-10 with IL-10R on epithelial cells for GC-establishing infection at the human cervix." (PMID 39585777, 2024). "Compared to the non-infection group, we observed elevated levels of the majority of measured cytokines (25/48) in the CSF during Mtb infection, including TNF-α, IFN-γ, IL-1β, IL-2, IL-3, IL-6, IL-8, IL-10, IL-12(p40), IL-17A, IL-18, IP-10, MIG, MCP-3, MIP-1α, and MIP-1β." (PMID 38047697, 2024). "Moreover, the suppression of proinflammatory cytokines like IL1β and IL18 enables M. tb to evade immune detection and reduces the recruitment of immune cells to the infection site." (PMID 39125766, 2024). "In addition, IL-1β expression increased 20-fold, while SAP components decreased 13-fold on day 20 after infection." (PMID 39766497, 2024). "Therefore, we employed ELISA to assess the levels of IL-1β, TNF-α, and IFN-α to analyze the different innate immune responses triggered by Del4L or ASFV-WT infection in pigs." (PMID 38501350, 2024). "Similarly, a study describing the in vitro infection of human primary monocytes indicated that SARS-CoV-2 also engages inflammasomes and promotes pyroptotic events, leading to enhanced levels of IL-1β." (PMID 39583156, 2024). "Nonetheless, infection of BMDMs with either L. major or L. tropica, even after LPS priming, did not lead to the secretion of IL-1b." (PMID 39696675, 2024). "Moreover, the secretion of IL-1β and TNF-α induced by Del4L infection was increased up to about 22 and 4 folds, respectively, higher than that induced by ASFV-WT infection in PAMs." (PMID 38501350, 2024). "Additionally, the levels of the pro-inflammatory cytokines IL-1β, IL-6, and TNF-α in serum samples collected from infected chickens at 24 h post-infection were detected." (PMID 39596124, 2024). "This is contrary to previous findings that infection with the opportunistic pathogen S. aureus stimulates IL‐8 production in nasal and intestinal epithelial cells, and activates C5AR1 to stimulate the production of IL‐1β in blood." (PMID 38666460, 2024). "Cerebrospinal fluid cytokine levels were elevated in 6 patients without infection before they became seizure free, and we detected increased IL-1β and IL-6 levels in these patients." (PMID 39006838, 2024). "IL-1β appears to be an especially key cytokine induced by BCG training: In BCG-stimulated monocytes, IL-1β levels increased after restimulation, conferring non-specific protection against the infection." (PMID 38892046, 2024).
infection (continued). "Also, in immunized horses with an attenuated vaccine, the transcriptome analysis of immune responses in PBMCs after in vitro infection with AHSV revealed the up-regulation of genes of different cytokines such as IL-6, TNF, CXCL2 and IL-1β." (PMID 38396742, 2024). "The infection, when performed by fish immersion in the viral suspension induces the expression of il1b from 24 to 48 hpi in the absence of induction of type-I ifn and isg15 gene expression." (PMID 39102417, 2024). "The expression levels of TNF-α, IL-1β, IP-10 and MIP-1α cytokines were analyzed in the WT, RvΔ0687 and C-Rv0687 strains in the cell-free post-infected supernatants of infected BMDMs at 1–5 days post-infection." (PMID 39063103, 2024). "Furthermore, the absence of the IL-22 cytokine exacerbates lung inflammation, resulting in significantly elevated levels of IL-1β, TNF-α, and IL-12 during infection." (PMID 39635124, 2024). "Additionally, we found that several cytokines and chemokines like IL-8, IL-1β, CXCL6, MCP-1 and MCP-4 were increased upon estradiol-stimulated CFT073 infection." (PMID 39362931, 2024). "Thus, after infection, monocytes from LPD-fed mice had decreased levels of Tnfaip2, whose expression is regulated by TNFα and other proinflammatory stimuli like IL1β and LPS via NFκB activation." (PMID 39349819, 2024). "The raw data show that there is very low expression of il1b and mmp9 in the absence of infection in all cases, as expected from the published literature for these markers in zebrafish larvae." (PMID 39336115, 2024). "Another study has reported that the positivity of IL-1β does not necessarily correspond with infection but with the change toward the pro-inflammatory profile that favors term delivery." (PMID 39065188, 2024). "Mice lacking IL-1β (IL-1β-/-) failed to recruit neutrophils to the gut during infection, which reduced tissue damage and prevented depletion of short-chain fatty acid (SCFA)-producing commensals." (PMID 38236896, 2024). "Cytotoxicity data for keratinocytes, fibroblasts and MUTZ-LC infection indicated that the significant differences in IL-1β expression are not directly correlated to cell death." (PMID 39208402, 2024). "Specifically, TNFα, IL-1β, IL-6, IL-10, and type I interferons (IFN-β) decreased early during infection in all three regimes of mice immunization with rVSV-HTNV-GP." (PMID 38341504, 2024). "We also measured the gene expression level of IL-1β in infected cells with L. monocytogenes, and the infection in both cells does not induce the gene expression of this cytokine when compared to the respective mock conditions." (PMID 38771057, 2024). "Overproduction of IL-1β (as we observed) characterises labour with or without infection by inducing the labour pathway, especially in IUI-associated PTB." (PMID 39165357, 2024). "Moreover, IL-1β (p = 0.014) and TNF-α (p = 0.001) cytokines were significantly upregulated by the infection, which was reduced (p < 0.05) by zingerone." (PMID 37626627, 2023). "The data obtained show that M. furfur activates the inflammasome by inducing the expression of Il-1β, Caspase-1, IL-18, and NLRP-3 after 4 h of infection, while the simultaneous addition of L. plantarum totally inhibits this activation, bringing them back to the control values." (PMID 38132754, 2023). "In contrast to the neutralization of IFN-γ and TNF or IL-1β, neutralizing IL-6 activity in the post-acute phase of infection did not improve the pathology or fibrotic sequelae post infection." (PMID 38077031, 2023). "In SARS-CoV-2 infection, regardless of infection severity, both IL-1α and IL-1β have high values, contributing to triggering cytokine storms and uncontrolled immune responses." (PMID 37510190, 2023). "In summary, these results indicate that mucosal delivery of Ad-HA/NP+Ad-IL-1β increased HA-specific IgG and IgA titers in serum and nasal swabs, and IgG responses in BAL, while pH1N1 infection resulted in higher IgA pH1N1 responses in serum, BAL, and nasal swabs." (PMID 37153548, 2023).
infection (continued). "The upregulation of the expression level of IL-1β, TNF-α, and Myd88 indicates that GF-7 supplementation might induce an immune response in M. salmoides, and enhance the body’s resistance to foreign infection." (PMID 37333660, 2023). "Therefore, the innate response to in vitro infection of macrophages with both LAMV and WT MeV includes production of IL-6 and TNFα and activation of the NLRP3 inflammasome to release IL-1β and IL-18." (PMID 36851476, 2023). "Elevated levels of key inflammatory chemokines and cytokines, such as CXCL10/IP-10 and IL-1β, were observed in nasal wash fluid and lung homogenate supernatants from hamsters during primary infection, but not after reinfection." (PMID 36633406, 2023). "Infection of PBECs led to induction of CXCL8, interleukin (IL)-1β, IL-6 and TNF." (PMID 37180449, 2023). "At week 4 post infection, CD4+ T-cells showed a mixed response to S. mansoni AWA by secreting cytokines which encompassed Th1 (IFNγ, TNFα, IL-2 & IL-1β), Th2 (IL-4, IL-5, IL-13) and regulatory responses (IL-10) as well as the regulatory T cell transcription factor Foxp3." (PMID 37837930, 2023). "Gene expression of multiple cytokines is raised in the conjunctiva during each stage of disease: IL-1β, TGF-β, TNF-α, IFN-γ, IL-2, IL-4, IL-12 p40 during infection; IL-1β, TGF-β, TNF-α, IL-17A, CCL18 and CXCL5 during active disease, and IL-1β, TGF-β and TNF-α in scarring." (PMID 37862368, 2023). "Notably, our results showed an upregulated transcriptional expression of cytokines (IL-1β, IL-6 and TNF-α), adhesion molecules (VCAM-1, ICAM-1) and chemokines (CXCL1 and CXCL2) after infection in both brain cortex and hippocampus." (PMID 36778380, 2023). "Furthermore, the combination of TMAO and CFT073 significantly increased the release of IL-1β and LDH compared to CFT073 infection alone." (PMID 37111409, 2023). "The absence of cytokines TNF-α and IL-1β resulted in decreased levels of infection, demonstrating that successful infection by T. cruzi requires some activation of NF-kB." (PMID 37242378, 2023). "Secondly, enhanced level of cytokines and chemokines (e.g.IL1B, IL6, CCL5-2, CXCL9-10, and TNFα) in the mother, placenta, and/or neonate was reported in SARS-COV-2 and ZIKV infections." (PMID 37700750, 2023). "Upon damage or infection, intracellular MIF can also interact with nitrogen permease regulator-like 3 (NLRP3) to facilitate the interaction between NLRP3 and vimentin, resulting in the release of IL1β." (PMID 38052787, 2023). "Here, high levels of cytokines and chemokines (TNF-α, IFN-γ, IP-10, IL-1β, and IL-6), with significantly upregulated TNF-α levels 24 h after infection could be detected." (PMID 37163429, 2023). "In contrast to macrophages, non-lytic expression of IL-1β enables neutrophils to maintain the concentration of this cytokine at the site of infection and perform protective functions." (PMID 37047314, 2023). "Compared with those produced by E. coli DH5α-injected mice, E. coli JE5505-injected mice produced high levels of TNF-α, IL-1β, and RANTES and a low level of IL-10 in their livers, lungs, and sera after infection at indicated time points (3 h or 6 h postinfection; P < 0.05)." (PMID 36916913, 2023). "Infection of neutrophils and HL-60 cells produce striking quantities of chemokines, including IL-8, RANTES, MIP1α, MIP1β, and MCP1, but not other cytokines observed with in vivo infection, including IFNγ, IL-10, TNFα, IL1β, or IL4." (PMID 37228668, 2023). "The downregulation of IL-1β and the modulation of the abundance of proteins involved in inflammasome activation implicates this immune sensing pathway and inflammatory, pyroptotic cell death in the response to MVA infection in human macrophages." (PMID 38065956, 2023). "The production of cytokine IL-1β showed no increase 3 h to 12 h after infection with S. aureus but rose abruptly at 24 h post infection." (PMID 37237611, 2023).
infection (continued). "We did not detect differences in liver IL-1β or IL-10 levels after infection, suggesting that local inflammation alone is not readily equated with the end-organ tissue damage observed." (PMID 37788087, 2023). "Other inflammatory makers, including IL-1α, IL-1β and IL-6, were not different between infection groups." (PMID 36748431, 2023). "In contrast to ST, Xiap−/− DCs did not display increased cell death in response to infection with LM and the secretion of IL-1b was not detectable." (PMID 37347786, 2023). "Surprisingly, there were no increases in the levels of either IL-1α or IL-1β after infection with the virulent isolate SY18 or its attenuated derived mutant, SY18ΔL7-11." (PMID 36680273, 2023). "We used qPCR to analyze 12 host-related genes, including those with no significant fold change (IL12A), modest (e.g. TNF, LMO1, IL10, CCL2, IL1B) or high fold change, including CXCL8 which was among the 50 identified to be most significantly dysregulated in monocytes as a result of infection." (PMID 36747074, 2023). "Regardless of the condition, infection with C. neoformans did not affect pro-IL-1β levels after 12 or 24 hpi as assessed by ELISA." (PMID 38033163, 2023). "We found that the treatment of BMDMs with TTN did not prevent pyrin PS205 dephosphorylation or IL-1β release in response to infection with ∆yopM Yptb." (PMID 37787552, 2023). "Furthermore, in our experiment, inflammation-related indicators in blood, such as WBC, CRP, IL-6, IL-1β and TNF-α, exhibited varying degrees of elevation since 18 h of infection." (PMID 37587524, 2023). "Overall, IL-1β was most markedly upregulated in the rHLJ0504 infection group within 7 dpi, whereas its upregulation was not significant in the rSHG19 infection group." (PMID 40303711, 2023). "In an earlier report, we showed that PAO1 infection of peritoneal neutrophils induced release of IL-1β that was attenuated (~50-60%) but not completely suppressed in neutrophils from caspase-1-/- and Nlrc4-/- mice." (PMID 37730693, 2023). "Furthermore, as demonstrated in an A. fumigatus mouse infection model, inflammasome activation via NLRP3 eventually provides immune protection and IL-1β-mediated survival." (PMID 36983500, 2023). "Incubation with either HMPV or SeV alone failed to significantly increase levels of mature IL-1β in the supernatant of human macrophage cell culture (left bars), despite the fact that virus indeed replicates at this timepoint of infection." (PMID 37435074, 2023). "Herein, we focused on the role of CVB3 in macrophages and found that CVB3 pre-infection in macrophages could significantly inhibit LPS-induced NLRP3 inflammasome activation and IL-1β production." (PMID 37243164, 2023). "Consistent with a pro-inflammatory state, LPS-preconditioning significantly increased EPO, IFN-γ, IL-1β, KC, TNF-α, MCP-1, MIP-1α, and IFN-β levels in the lungs and pulmonary FTT infection significantly reduced IFN-γ, IFN-β, and MMP9 levels among LPS preconditioned mice." (PMID 37883420, 2023). "At 3 days post-infection, intravenous administration of hMSCs significantly decreased the concentrations of pro-inflammatory cytokines and chemokines, i.e. TNF-α, IL-1β, MCP-1, CXCL1 in lung homogenate and/or BAL fluid, respectively, as compared with mice treated with NHLFs group." (PMID 37704783, 2023). "Treatment with CNP-miR146a four hours after infection resulted in significantly decreased relative gene expression of TRAF6 (p = 0.01), NF-κB (p = 0.003), IL-6 (p = 0.01), MIP-2 (p = 0.005), IL-1β (p = 0.01), and TNFα (p = 0.003) compared to untreated, MRSA-infected lungs." (PMID 37765178, 2023). "Macrophages exposed to L. braziliensis products through the membrane produced more IL-1β upon infection than those that were not previously exposed to parasite factors." (PMID 37841240, 2023).
infection (continued). "However, this study also found that Ehx contributed to THP-1 cell toxicity and showed a positive correlation between IL-1β secretion and LDH release to the supernatants upon infection with Ehx-expressing bacteria." (PMID 38127952, 2023). "IL-1β is a typical proinflammatory cytokine released by monocytes, macrophages, and non-immune cells in response to cellular injury and infection." (PMID 40303711, 2023). "In mice, R7 more effectively protected mice from infection with MDR E. coli or LPS and alleviated inflammation than its parental peptides by inhibiting the production of proinflammatory cytokines (TNF-α, IL-6, and IL-1β) and promoting IAP and IL-10." (PMID 37973936, 2023). "Following the initial infection of the lungs by SARS-CoV-2, a cytokine storm is generated, characterized by the release of various cytokines such as tumor necrosis factor-alpha (TNFα), interleukin-1β (IL-1β), and IL-6." (PMID 38162133, 2023). "Meanwhile, dietary EOA treatment also upregulated CLDN-1, OCLN, ZO-1, MUC2 and FABP2 mRNA levels at the middle infection phase, as well as linearly reduced the gene expression level of TLR4, NF-κB and IL-1β at the early infection stage in infected broiler chickens." (PMID 37391807, 2023). "The disruption of IL-1β and NLRP3 can lead to impairment of the innate cellular immune response, which may have varying clinical implications during infections." (PMID 36905446, 2023). "To determine whether OI-14-15 regulates noncanonical inflammasome activation directly or by manipulating the TLR-dependent IFN or pro-IL-1β synthesis, we assessed the levels of IFNβ and pro-IL-1β as well as IL-6 and TNF at early stages of infection." (PMID 37041208, 2023). "Interestingly, in the first phase (up to day 3 post-infection), the expression of NLRP3, IL-1β, and IL-18 was significantly upregulated in several organs before viremia was detectable in blood." (PMID 36800238, 2023). "Consistent with our findings and those of others, which indicate that expression and release of the inflammasome-dependent cytokine IL-1β are very low in human IECs, we did not detect IL-1β release during Δ6 Yptb infection." (PMID 37615436, 2023). "Pro-inflammatory cytokines, IL-1β and IFN-γ, promote the output of innate immune effector cells to address infection at the expenses of reduced bone marrow erythropoiesis, however, TNF-α and IL-1β facilitated the expansion and differentiation of stress erythroid progenitor cells in the spleen." (PMID 37180169, 2023). "Longer pretreatment of BMDMs with 1 μM TTN also did not decrease IL-1β secretion upon ∆yopM infection (unpublished observation)." (PMID 37787552, 2023). "Absence of the inflammatory cell infiltrates critical for early resolution of infection demonstrates the absence of inflammatory chemotactic signaling, despite elevated Il-1β." (PMID 37069680, 2023). "This coincided with reduced serum levels of pro-inflammatory (IL-1β, TNFα, and KC/GRO) and anti-inflammatory markers (IL-10), increased bacterial killing ability of macrophages, and reduced macrophage infiltration into to site of infection." (PMID 36831019, 2023). "At 12 h post-infection, THP-1 macrophages secreted higher levels of TNF-α, IL-6, IL-1β and IFN-γ compared with untreated/uninfected controls, with the Mel˗ conidia group showing significantly higher levels of all four factors compared with the Mel+ conidia group (P < 0.05)." (PMID 37141335, 2023). "A degree of co-expression of genes with proposed opposing effects on M.tb, e.g., IL1B and IFNG (better control) versus IDO1 and Type 1 IFNs (reduced control) – suggests counteracting influence on growth during the early phase of infection and requires further experimentation." (PMID 37333188, 2023). "After intratracheal infection with Pseudomonas aeruginosa, KO mice showed increased mortality, higher injury scores, more severe inflammation in the lung and kidney, and increased serum TNF-α, IL-1β, and IL-6 levels compared to WT and hTG mice." (PMID 37256132, 2023).